HMGCL (3-hydroxy-3-methylglutaryl-CoA lyase)
Diseases named in the same sentence as HMGCL in open-access papers (continued):
Sharing a sentence is not in itself a finding about the gene and the disease.
tumor (14 papers, 2017 to 2025). "Downregulation of HMGCL was associated with a larger tumor size and a shorter overall survival time." (PMID 36923932, 2023). "Genomic enrichment analysis (GSEA) of this proteomic data showed that the low expression of HMGCL was associated with oncogenic EMT and E2F signaling, whereas the enriched dataset with high HMGCL was associated with bile acid metabolism and peroxisome, which are involved in anti-tumor activity." (PMID 36508088, 2023). "Consistently, pan-cancer gene expression analysis showed that HMGCL mRNA was differentially expressed in different tumor types." (PMID 36508088, 2023). "The mechanism of HMGCL-mediated tumor suppression was studied by IHC, western blot (WB) and Cut & Tag." (PMID 36508088, 2023). "At 6 weeks after injection, HMGCL depletion led to increased tumor number, size and liver weight/body ratio, as well as aspartate aminotransferase (AST) and alanine transaminase (ALT) concentration in serum." (PMID 36508088, 2023). "To confirm the in vitro results, we further investigated the effect of altered HMGCL expression on tumor proliferation and metastasis in vivo." (PMID 36508088, 2023). "Through the analysis based on TCGA database, HMGCL expression was heterogeneous in pan-cancer, leading to multiple HMGCL effects in different tumor types." (PMID 36508088, 2023). "Meanwhile, HMGCL was down-regulated in HCC tumor lesions according to the results of proteomics data in public databases (n = 101)." (PMID 36508088, 2023). "Consistent with the protumor effect of BHB, AcAc produced by upregulated HMGCL or KD promoted tumor cell growth and proliferation in BRAF V600E-expressing melanoma." (PMID 36432618, 2022). "This led us to suggest that HMGCL functions as a potential tumor suppressor in NPC by increasing the intracellular β-hydroxybutyrate." (PMID 31921677, 2019). "Moreover, the HMGCL protein level was negatively correlated with tumor size and positively correlated with survival." (PMID 36923932, 2023). "To determine whether the effect of HMGCL expression on tumor suppression could be reproduced in vivo, we subcutaneously injected HMGCL-5-8F and pCMV6-Entry-5-8F cells in opposite flanks of nude mice." (PMID 28931870, 2017). "The MREs ACAT1, ACAT2, FDFT1, FDPS, HMGCL and PMVK were highly expressed in basal tumor cells and urothelial cells." (PMID 39521858, 2024). "We quantified the HMGCL expression level of HCC in 11 pairs of HCC and matched non-tumor liver tissues (NLTs) and other samples including 3 cases of normal liver tissues, 3 cases of non-metastatic HCCs and 3 cases of metastatic HCCs by WB." (PMID 36508088, 2023). "Since overexpression of each of these genes inhibited growth/proliferation and migration/metastasis of these cancer cells, genes for ketogenic enzymes such as HMGCS2, ACAT1, HMGCL, and BDH are suggested to be potential tumor suppressors." (PMID 36432618, 2022). "Ketone bodies are also major energy sources for mitochondria and they are synthesized in tumour stroma with the help of enzymes, such as HMGCS2, HMGCL, BDH1, and re-utilised in tumour cells." (PMID 28373964, 2017). "Furthermore, we detected correlation between HMGCL depletion and poor prognosis of HCC patients, including microvascular invasion, elevated APF level, increased tumor size, poor differentiated stage and poor pTNM characteristic." (PMID 36508088, 2023). "In summary, HMGCL was downregulated in NPC cells and tumor tissues." (PMID 28931870, 2017). "Notably, the protein expression patterns helped to differentiate non-malignant proliferative cells from tumor-derived models, most clearly through the selective upregulation of HMGCL in HepaFH3 cells and c-MYC in HCLs." (PMID 40862732, 2025).
cancer (9 papers, 2017 to 2025). A tumor composed of atypical neoplastic, often pleomorphic cells that invade other tissues. "IVD and HMGCL are pivotal in the catabolism of leucine, affecting energy production and lipid metabolism, which are vital for cancer cell viability." (PMID 39286249, 2024). "HMGCL as the key enzyme to promote the conversion of HMG-CoA to ketone bodies, had been linked to several cancers." (PMID 36508088, 2023). "The roles of HMGCL in cancers seem to be dependent on the context." (PMID 36923932, 2023). "To date, only a few studies have verified the role of HMGCL in human cancers." (PMID 28931870, 2017). "In addition, there have been contradictory reports of the role of HMGCL in human cancers." (PMID 38551020, 2024). "The downregulation of HMGCL and IVD in COAD tumors compared to normal tissues could be indicative of a metabolic shift that favors anabolic processes over catabolic ones in cancer cells." (PMID 39286249, 2024).
metabolic disorders (4 papers, 2023 to 2025). "3-hydroxy-3-methylglutaryl-CoA (HMG-CoA) lyase deficiency is a rare autosomal recessive metabolic disease caused by variants in the HMGCL gene leading to an impairment in leucine catabolism and ketone synthesis." (PMID 41323099, 2025).
infection (1 paper, 2018). The state of being infected such as from the introduction of a foreign agent such as serum, vaccine, antigenic substance or organism. "Upon a LPS simulation, only one expression peak was detected for HMGCL at 6 hours post infection (hpi) with a 4.4-fold increase compared with the control, and the level of expression was significantly higher than that from 12 to 72 hpi." (PMID 29416598, 2018).
neurodegenerative disease (1 paper, 2020). A disorder of the central nervous system characterized by gradual and progressive loss of neural tissue and neurologic function. "HMGCL can induce cholesterol synthesis, which is critical in neurodegenerative disease; hence, we measured the cholesterol level in the brain." (PMID 32127052, 2020). "Moreover, we were interested in the role of HMGCL, an enzyme involved in the synthesis of cholesterol, which is critical in neurodegenerative disease." (PMID 32127052, 2020).
HMGCL also shares sentences with these, for which no sentence is quoted: Hypoglycemia (3 papers); prostate carcinoma (3); hairy cell leukemia (2); hepatocellular carcinoma (2); maple syrup urine disease (2); organic acidemias (2); 21-Hydroxylase deficiency (1); 3-methylglutaconic aciduria type 5 (1); acute myeloid leukemia (1); Argininemia (1); cardiomyopathy (1); cardiovascular diseases (1); congenital adrenal hyperplasia (1); cystic fibrosis (1); diabetes (1); dilated cardiomyopathy (1); ethylmalonic encephalopathy (1); genetic disorder (1); glioma (1); glutaric acidemia type 1 (1); gout (1); Hartnup disorder (1); Hyperammonemia (1); Methylmalonic aciduria (1); methylmalonic aciduria type mut (1); multiple acyl-CoA dehydrogenase deficiency (1); multiple carboxylase deficiency (1); neuroblastoma (1); Obesity (1); ornithine transcarbamylase deficiency (1).
A further 8 diseases each share a sentence with HMGCL in 1 paper.